MITF (melanocyte inducing transcription factor)
Diseases named in the same sentence as MITF in open-access papers (continued):
Sharing a sentence is not in itself a finding about the gene and the disease.
melanoma (continued). "In summary, these data suggest that CD271 likely controls melanoma cell migration and metastasis via phenotype switching which includes the suppression of MITF-targets." (PMID 32878000, 2020). "MG132, a specific proteasome inhibitor, partially recovered the MITF protein in the presence of ACF, potentially indicating that ACF decreased MITF protein stability in melanoma cells." (PMID 33396270, 2020). "To address this issue, we performed chromatin immunoprecipitation coupled to high-throughput DNA sequencing (ChIP-seq) using an established 501mel melanoma cell line expressing hemagglutinin (HA)-epitope-tagged MITF." (PMID 32531202, 2020). "In this study, we investigated the function of microphthalmia-associated transcription factor (MITF), which contributes to the development of melanoma, in epithelial ovarian cancer (OvCa)." (PMID 33371469, 2020). "Although dermoscopic patterns of melanocytic nevi in MITF+ and MITF− patients have already been reported, our study is the first to assess the dermoscopic characterization of DN and melanomas in MITF+ patients compared to MITF− patients." (PMID 32054529, 2020). "Microphthalmia-associated Transcription Factor (MITF) is a lineage-determining transcription factor critical for regulation of the melanocytic lineage during development and implicated as both a melanoma tumor suppressor and oncogene." (PMID 32850759, 2020). "The overall contribution of recently identified CM predisposition genes (ACD, BAP1, POT1, MITF, and TERF2IP) to melanoma’s missing heritability is estimated to be about 2%." (PMID 32325837, 2020). "A downregulation of MITF in melanoma cells has been related to an invasive/poorly proliferative phenotype, increased plasticity and acquired therapy resistance to BRAF inhibition." (PMID 33167306, 2020). "This complicated multifaceted role of MITF in melanoma is also reflected in its role in the mechanisms of resistance to BRAF inhibition." (PMID 32605090, 2020). "MITF is amplified in circa 20% of melanoma tumors, and this is thought to contribute to tumor progression." (PMID 32605315, 2020). "Accordingly, analysis of a previously published dataset shows that PTGS2 and MITF are regulated in an inverse manner after TNFα treatment in melanoma cells." (PMID 32978520, 2020). "The tumor microenvironment of melanoma is shaped by the level of MITF expression and depletion of MITF stimulates the release of inflammatory cytokines such as IL-6 and IL-1β." (PMID 33293474, 2020). "ZEB2 silencing in mouse NRASQ61 melanoma cells decreases MITF, increases ZEB1, and induces proliferation defects." (PMID 32759677, 2020). "XL888 resistance mechanism involving CDK2 was identified in melanoma cells, and CDK2 expression was dependent on MITF (microphthalmia-associated transcription factor)." (PMID 31659567, 2020). "As MITF is a known regulator of both differentiation and proliferation in melanoma cells, we examined MITF expression in RANKL‐treated melanoma cells." (PMID 31323160, 2020). "Collectively, our findings reveal that POU4F1 re-activates the MAPK pathway by transcriptional regulation on MEK expression and promotes MITF expression, which ultimately results in the resistance to BRAFi in melanoma." (PMID 32532957, 2020). "SOX10 binds in the promoter region of MITF and hence is expressed in all congenital naevi and melanomas." (PMID 32899370, 2020).
melanoma (continued). "MITF+ patients showed more frequently dysplastic nevi and melanomas with uncommon dermoscopic patterns (unspecific), as opposed to MITF− patients, whose most prevalent pattern was the multicomponent." (PMID 32054529, 2020). "In contrast, MITF-M, the main isoform of MITF in melanocytes and melanoma cells has been shown to be primarily nuclear." (PMID 32881934, 2020). "Similar to their observed roles in melanocyte homeostasis, the ZEB transcription factors seem to have opposing roles in melanoma that converge at the expression level of MITF." (PMID 32796736, 2020). "Accordingly, the expression of MITF has been widely used as a marker to distinguish between the proliferative and invasive types of melanoma cells." (PMID 33202765, 2020). "Determining the expression levels of MITF and other factors that promote metastasis and phenotype switching, allows to distinguish between melanoma cells that are sensitive or resistant to BRAF inhibitor." (PMID 33167306, 2020). "To further characterize the RANKL‐RANK‐MITF signalling axis, we first used RNAi to deplete MITF in melanoma cells prior to RANKL stimulation." (PMID 31323160, 2020). "So far we observed that CM from differentiated osteoblasts not only induces MITF expression, but also activates NFκB signalling in melanoma cells." (PMID 31323160, 2020). "In summary, one of the main hurdles to achieving fully effective immunotherapy is the plasticity of melanoma cells, in which MITF plays a pivotal role." (PMID 33276788, 2020). "In line with this, melanoma cells with high β-catenin and high MITF levels have been characterized with an elongated filopodia phenotype and MITF reduction significantly increased rounded blebbing cells." (PMID 32659938, 2020). "Both MAPKi-resistant BRAFV600E-mutated melanoma cell lines and tumour biopsies obtained from human MAPKi-resistant BRAFV600E patients express high levels of ZEB1 but low levels of ZEB2 and MITF." (PMID 32796736, 2020). "Altogether, these data support an MITF‐dependent role for the RANKL‐mediated increase in melanoma survival upon BRAF inhibition." (PMID 31323160, 2020). "Considered as one of the leading melanogenesis regulators, MITF is generally amplified in roughly 20% of melanoma patients." (PMID 33126560, 2020). "Even though such an expression pattern can be observed in cells unexposed to BRAF inhibitors, a low MITF/high AXL pattern would be increased as the melanoma progresses." (PMID 32605090, 2020). "Specifically in melanoma, the transcription factor MITF is impacted by the EMT process, with ZEB1 and HIF1A being potent repressors of MITF expression." (PMID 32899370, 2020). "On the contrary, the MITF level and expression of several MITF-dependent genes are markedly reduced in vemurafenib-resistant melanomas resulting in more primitive phenotypes of melanoma cells." (PMID 31624899, 2020). "In contrast to their expression in lung adenocarcinoma, VEGFC and PFGFC are upregulated by silencing MITF in melanoma cells, which is in accordance with MITF low-expression promoting metastasis because angiogenesis usually accelerates metastasis." (PMID 33293474, 2020). "Next, we tested if the 36 active compounds from the IFNγ HTRF assay and the cell viability assay can affect expression of genes that regulate melanoma cells differentiation and pigmentation such as MITF, DCT, Melan-A and Tyrosinase-related protein 1(Tyrp)." (PMID 32231230, 2020). "We further noted that less than 30% of the MITF bindings sites found in the three melanoma cell lines COLO829, MM031, and MM011, for which public data on MITF Chip-seq were available, overlapped." (PMID 32605315, 2020). "It has also been shown that MEK and BRAF inhibitors can increase the number of macrophages, as well as their expression of tumor necrosis factor-α (TNF-α), mediating upregulation of MITF expression in melanoma cells through NF-κB activation." (PMID 33291749, 2020).
melanoma (continued). "In the tumor stroma, MAPK inhibition enhances the recruitment of tumor-associated macrophages that, through TNFα release, increase the expression of MITF in melanoma cells." (PMID 32466585, 2020). "Characterizing primary melanoma cultures according to their MITF levels revealed an inverse correlation between LTR5_Hs/HERV-K RNA levels and invasiveness." (PMID 33202765, 2020). "High levels of ZEB1/TWIST1 expression undoubtedly promote an invasive phenotype in melanoma, including decreased E-Cadherin, MITF, and increased expression of Vimentin, SPARC, and MMPs." (PMID 32759677, 2020). "We found that BET inhibition suppressed expression of 36% of validated MITF target genes in Melb-a cells, half as many as in melanoma cells." (PMID 32151278, 2020). "The most striking links between MITF and the immune responses were identified in a recent study using four syngeneic models recapitulating diverse subtypes of human melanoma and the diversity of clinical responses to ICT." (PMID 33276788, 2020). "Ordóñez found that the sensitivity and specificity of MITF is lower than other melanoma biomarkers." (PMID 33339193, 2020). "Here we show that NRF2 suppresses the activity of the melanocyte lineage marker MITF in melanoma, thereby reducing the expression of pigmentation markers." (PMID 32978520, 2020). "The first one is the upregulated axis MITF-PGC1α, which is well established in drug-resistant melanoma cells, and is responsible for activated OXPHOS and unavoidable ROS generation." (PMID 33091721, 2020). "According to this model, depending on the levels of its expression and activity, MITF signaling can result in both inhibition and promotion of melanoma growth." (PMID 32245160, 2020). "A combination of MAPK pathway inhibition with IκB kinase (IKK) inhibitors improves the therapeutic response, diminishing MITF expression in melanoma cells and blocking TNFα activity in tumor stroma." (PMID 32466585, 2020). "In melanoma, GH upregulates the melanocyte-inducing transcription factor (MITF), that targets the oncogene MET, and organizes the resistance to radiation therapy." (PMID 33312162, 2020). "Next to this, GLI family zinc finger 1 (GLI1) is proposed to be important for maintaining the invasive properties of melanoma cells in a ZEB2/MITF-independent manner but most likely ZEB1-dependent manner." (PMID 32796736, 2020). "Such agents include alpha-melanocyte-stimulating hormone (α-MSH) and cAMP-elevating agents, such as forskolin that were reported to increase the levels of MITF and melanoma antigens such as MART-1 and GP-100." (PMID 33276788, 2020). "Regarding miR-137, it has been observed that miR-148 negatively regulates MITF expression in melanoma cells by targeting a binding site found in its 3′UTR sequence." (PMID 32013263, 2020). "Analysis of two MITF ChIPseq datasets showed that MITF binds to intronic regions of KCND3 in 501mel melanoma cells." (PMID 32193365, 2020). "Melanoma cells with high cellular MITF-level are proliferative, those with low levels show a stem cell-like invasive phenotype." (PMID 32455577, 2020). "Investigation of the clinical significance of MITF expression in melanoma samples showed its positive correlation with survival." (PMID 32429485, 2020). "It has to be noted that some other transcriptional factors are also involved in MITF activation in the formation of BRAFi resistance in melanoma." (PMID 32532957, 2020). "Clinical trials: In melanoma, MITF and its upstream activator, PAX3, are drivers of an early non-mutational and reversible drug-tolerant state." (PMID 33322354, 2020). "On the other hand, MITF, a melanoma lineage-specific gene, is also an important player in the immunogenicity of the disease." (PMID 32245160, 2020).
melanoma (continued). "MITF represents a melanocytic lineage-specific transcription factor that regulates melanocyte differentiation, function and survival as well as melanoma progression." (PMID 32858889, 2020). "Further, Hermes 4C cells display increased MITF chromatin binding, and transcriptional reprogramming consistent with an invasive melanoma phenotype." (PMID 32605315, 2020). "It was recently demonstrated that MITF expression increased in AC-overexpressing melanoma cells and observed that AC expression was higher in human melanoma cells exhibiting a proliferative phenotype as compared to invasive ones." (PMID 33121001, 2020). "According to the “MITF rheostat” model, different expression levels of MITF are connected with specific phenotypic states of melanoma cells." (PMID 33167306, 2020). "MITF has also been found to regulate phenotype switching, wherein low expression leads to increased invasiveness of melanoma cells and high expression leads to decreased invasiveness." (PMID 32429485, 2020). "TYRP1 expression was MITF-M-independent, since in all BRAFV600E melanoma cell lines, both MITF-Mhigh and MITF-Mlow, levels of TYRP1 transcript were similar." (PMID 31624899, 2020). "SOX10 binds and interacts with MITF or other pro-differentiation transcription factors, thereby promoting the development of melanoma." (PMID 33344444, 2020). "MITF protein levels were downregulated in a dose dependent manner by ACF in several melanoma cell lines as demonstrated by western blot and confocal microscopy." (PMID 33396270, 2020). "It is possible that regulation of TYRP1 expression in MITF-Mlow melanoma cells is stabilized by other transcription factors or regulatory mechanisms." (PMID 31624899, 2020). "For instance, canonical Wnt signalling through the Wnt/β-catenin pathway is a critical activator of MITF expression in melanoma cells, and deactivation correlates with a higher metastatic potential." (PMID 32858889, 2020). "Other studies showed that the MITF-PGC1α axis is downregulated in melanoma cells and has a tumor-suppressing role." (PMID 33091721, 2020). "When analyzing publicly available RNA sequencing datasets from melanoma cell lines, we found that the knockdown of MITF leads to a profound induction of PTGS2." (PMID 32978520, 2020). "A significant correlation between TYRP1 mRNA level and MITF level was found also in a subset of melanoma cell lines." (PMID 31624899, 2020). "It was reported that the inhibition of the ERK signaling pathway induces melanoma cell proliferation and MITF activity in vitro suggesting that the ERK signaling pathway negatively regulate MITF-mediated melanogenesis." (PMID 33260669, 2020). "Meanwhile, the encoding gene of survival associated mitochondrial melanoma-specific oncogenic lncRNA (SAMMSON) also harbours the melanoma-specific oncogene MITF and it was demonstrated that SAMMSON is frequently co-amplified with it." (PMID 33203119, 2020). "Taken together, these papers suggest that activation of TGF-β signalling is important during the initial downregulation of MITF and the melanoma differentiation signature." (PMID 32796736, 2020). "The MITF level is enhanced in BRAFV600E melanoma cells upon acute exposure to vemurafenib, and MITF inhibition increases sensitivity of cells to this inhibitor." (PMID 31624899, 2020). "Amplifications of the MITF gene were demonstrated in 10% of samples in a study by the Melanoma Genome Project group and the amplifications were noted in all the melanoma subtypes included in this study." (PMID 32605090, 2020). "Melanoma cells are characterized by an either high or low MITF expression signature, which confers the following corresponding functional characteristics: strong MITF expressing cancer cells are highly proliferative, but neither invasive nor metastatic." (PMID 32899370, 2020). "In this study, we have explored the role of PTEN in prognosis, therapy response, and immune escape in the context of MITF expression in melanoma." (PMID 32245160, 2020).
melanoma (continued). "It is now well accepted that melanoma cells expressing moderate to high levels of MITF proliferate rapidly and are poorly invasive, whereas melanoma cells characterised by low MITF levels grow more slowly and are more invasive." (PMID 32858889, 2020). "Which function mediated by ANXA1 in the context of MITF regulation in lung adenocarcinoma and melanoma progression, and how MITF regulates ANXA1 warrant further investigation." (PMID 33293474, 2020). "A wide range of cellular stresses including hypoxia, low glucose and inflammatory signaling were shown to reduce MITF expression and increase the metastatic properties of melanoma cells." (PMID 33121001, 2020). "Although MITF has been extensively investigated in the progression of the melanocyte/melanoma linage, few studies have demonstrated the role of MITF in lung cancer." (PMID 33293474, 2020). "The model based on MITF-mediated phenotype switching describes the reversible transitions of melanoma cells." (PMID 32759677, 2020). "The MITF-M isoform (hereafter simply designated as MITF) is the master regulator of melanocytes and has been identified as an addictive oncogene in melanoma." (PMID 33276788, 2020). "In our assay using BRAF mutant melanoma cells, 4 active compounds were identified that up-regulated the antigen, gp100 and the master regulator MITF." (PMID 32231230, 2020). "It was striking to note that the effects of RANKL were broadly similar when comparing a number of melanoma cell lines, known to express different levels of MITF." (PMID 31323160, 2020). "We found that POU4F1 and MITF were parallelly increased in Vemurafenib-resistant melanoma cells compared with parental cells." (PMID 32532957, 2020). "The expression of the main genes involved in the MITF pathway, which is a cell signal that plays a crucial role in melanoma progression, was analyzed by RT-PCR." (PMID 33080917, 2020). "Recently, a differentiation model of melanoma has been proposed, in which the level of MITF is one of crucial factors determining subtypes of melanoma exerting differential vulnerability to drug-induced stress." (PMID 32659938, 2020). "In conclusion, this study demonstrates that reversible acetylation of HINT1 at K21 and K30 by CBP and SIRT1 modulates the capacity of HINT1 to bind to β-catenin or MITF and in turn to control tumorigenic features in colon cancer and melanoma cells." (PMID 32636443, 2020). "Of the 22 MITF+ patients, 5 had a positive family history of melanoma, whereas the remaining 17 were apparently sporadic cases." (PMID 32054529, 2020). "A previous study reported that most melanoma cells contain hyper-activated MAPKs, which triggers MITF phosphorylation at serine 73, leads ubiquitin-mediated proteasomal degradation." (PMID 33260669, 2020). "Goding and collaborators (2011) proposed that the MITF activity correlates with the phenotype switching in melanoma tumor cells." (PMID 33167306, 2020). "In melanomas, MITF functions downstream oncogenic pathways and microenvironment stimuli that restrain the immune responses." (PMID 33276788, 2020). "We evaluated the expression correlation of MITF and its targets between lung adenocarcinoma and melanoma by TCGA PanCancer Atlas database with cBioPortal analysis." (PMID 33293474, 2020). "Numerous genes have been associated with melanoma: beyond CDKN2A and CDK4, primarily included as high-risk genes for familial melanoma, BAP1, POT1, and MITF were recently also identified as potential high-risk melanoma susceptibility genes." (PMID 33322357, 2020). "They found that a subset of melanoma cells with melanocyte inducing transcription factor (MITF)-driven overexpression of PGC1a display increased mitochondrial oxidative metabolism and ROS detoxifying abilities to withstand significant oxidative stress." (PMID 32046099, 2020).